MUC5AC (mucin 5AC, oligomeric mucus/gel-forming)
Diseases named in the same sentence as MUC5AC in open-access papers (continued):
Sharing a sentence is not in itself a finding about the gene and the disease.
diabetes (4 papers, 2020 to 2023). "MUC5AC concentration and goblet cell density in tear samples pre and post vitreo-retinal surgery sub-grouped based on Diabetes Mellitus status, age and gender." (PMID 32437405, 2020). "Age, gender and presence of diabetes did not significantly alter the tear MUC5AC concentration after VR surgery." (PMID 32437405, 2020).
emphysema (4 papers, 2016 to 2024). "Also, the signs of emphysema at the follow-up visit were associated with lower MUC5B expression, higher MUC5AC expression, and higher MUC5AC concentration in BW at baseline." (PMID 39769414, 2024). "We speculate that high MUC5AC expression and low MUC5B expression might be biomarkers primarily reflecting smoking exposure and thus associated with the risk of developing emphysema and bronchial wall thickening and with the progression of chronic airflow limitation in the long run." (PMID 39769414, 2024). "Consistent with lung function, subjects who had emphysema on CT scan at follow-up visit had lower MUC5B expression in goblet cells and higher concentration of soluble MUC5AC in the bronchial wash at baseline." (PMID 39769414, 2024). "In line with this, patients with emphysema had higher MUC5AC expression in goblet cells and higher MUC5AC concentration in BW fluid, as compared with patients without emphysema." (PMID 39769414, 2024). "In the current study, the values of MUC5AC expression in poly(I:C)-treated differentiated HBECs were inversely related to FEV1% predicted and DLCO/VA % predicted, which reflects damage to the alveolar capillary surface in patients with emphysema." (PMID 27677339, 2016). "Serine protease inhibition by ONO-3403, but not CM, significantly decreased KC expression and tended to decrease Muc5ac expression, suggesting that ONO-3403-dependent improvement of pulmonary dysfunction and emphysema is probably due to the lowering effect on KC and Muc5ac gene expression." (PMID 27982104, 2016).
gastritis (4 papers, 2020 to 2025). Inflammation of the stomach. "In particular, LCN2 expression levels were higher in MUC6+, MUC5AC+, proliferation cells, and in the chief cells in pre-GC and GC than gastritis." (PMID 40520011, 2025). "H. pylori colonises the surface mucous gel and manipulates mucin expression (for example, downregulating MUC5AC), enabling closer epithelial access, chronic inflammation and progression along the gastritis–atrophy–metaplasia–cancer cascade." (PMID 41511329, 2025). "α-Humulene may attenuate HCl/ethanol-induced gastritis by inhibiting histamine release and NF-κB activation and stimulating antioxidants and mucosal protective factors, particularly Muc5ac and Muc6." (PMID 34064830, 2021).
hepatocellular carcinoma (4 papers, 2020 to 2023). A malignant tumor that arises from hepatocytes. "Our study provides evidence of the potential involvement of MUC5AC in the etiology of hepatocellular carcinoma (HCC)." (PMID 37193028, 2023). "Importantly, MUC5AC is not expressed in hepatocellular carcinoma (HCC), suggesting a different biological pathway and assigning this biomarker an important role in diagnosis differentiation." (PMID 37628976, 2023).
ovarian mucinous tumors (4 papers, 2005 to 2019). "Goblet cells of the appendix express both MUC2 and MUC5AC mucins but primary ovarian mucinous tumors only express MUC5AC." (PMID 15967038, 2005). "Expression of several gel-forming mucins has been described for mucinous ovarian tumors such as MUC2, MUC5AC and MUC5B." (PMID 26075384, 2015).
pancreatitis (4 papers, 2011 to 2023). Inflammation of the pancreas. "In some cases, patients that were low in total CA 19-9 were distinguishable from pancreatitis patients by their CA19-9 level on MUC16 or MUC5AC." (PMID 22220206, 2011). "Each of the proteins MUC1, MUC5AC, and MUC16 showed significantly higher levels in the cancer patients than in the pancreatitis patients, both for early and late stage cancers." (PMID 22220206, 2011). "MUC5AC was not expressed in normal and pancreatitis tissues, and it was detected in PDA which is consistent with prior studies." (PMID 37835525, 2023). "Thresholds could be set by which several cancer patients but no pancreatitis patients were elevated in either CA 19-9 on MUC5AC or CA 19-9 on MUC16 but not in total CA 19-9." (PMID 22220206, 2011).
pyloric gland adenoma (4 papers, 2012 to 2026). A rare neoplastic polyp that arises from the stomach. "Pathological examination of the resected specimen revealed that a pyloric gland adenoma, which was positive for MUC6 and MUC5AC, had detached from its mucosal stalk, leading to significant hemorrhage." (PMID 42078163, 2026). "These tumours did not arise from pyloric gland adenomas, but displayed a similar immunophenotype with positive expression of MUC5AC and MUC6 and negativity for MUC2 and CDX2." (PMID 23206236, 2012). "The pyloric gland adenoma showed focal positive staining for MUC1, and negative staining for MUC2, as well as superficial staining for MUC5AC, and positive expression of MUC6 and VEGF." (PMID 23206236, 2012).
tubular adenoma (4 papers, 2006 to 2023). A usually polypoid neoplasm arising from the glandular epithelium. "Incidence of MUC5AC Ab positivity was higher in patients with tubulovillous adenoma than patients with tubular adenoma (66.7%–38.5%; p > 0.05)." (PMID 16409634, 2006). "MUC5AC antibody positivity was seen in 66.6% of hyperplastic polyps, 40% of tubular adenoma, and 67% of tubulovillous adenoma." (PMID 16409634, 2006). "The highest expression of MUC5AC was observed in serrated adenomas followed by tubular adenomas." (PMID 20929551, 2010). "Here, we assessed GS‐II binding and performed immunostaining for HIK1083 (specific to terminal αGlcNAc residues), MUC5AC, MUC6, and special AT‐rich sequence binding protein 2 (SATB2) in SSLs, MVHPs, and tubular adenomas (TAs)." (PMID 37036163, 2023). "Immunohistochemical expression of MUC5AC, MUC6, and HIK1083 in tubular adenoma and sessile serrated lesion." (PMID 37036163, 2023). "Expression of colonic mucins (MUC1, MUC4, MUC17, MUC2, and MUC5AC) and O-glycans [Sialyl LewisA (CA19-9) and Tn/Sialyl-Tn on MUC1] were analyzed in HP (n=33), SSA/P (n=39), and tubular adenoma (TA) (n=36) samples by immunohistochemistry." (PMID 27705923, 2017).
alveolitis (3 papers, 2014 to 2025). "Treatment of T-bet-/- mice with a monoclonal anti-CCL2 antibody enhanced NiNP-induced mucous cell metaplasia and MUC5AC mRNA levels (p < 0.05), yet marginally reduced NiNP-induced alveolitis." (PMID 24499286, 2014). "Furthermore, CYP exposure in the allergic pneumonitis rats resulted in more increase (p < 0.003) in MUC5AC and p38 gene expression (respectively); meanwhile, the IL-13 and STAT6 (respectively) showed a further decrease (p < 0.05), in comparison to the allergic pneumonitis-only group." (PMID 37048067, 2023). "The IL-13, MUC5AC, STAT6, and p38 mRNA expression showed a significant rise (p < 0.001) in the allergic pneumonitis group when compared to the control gene values." (PMID 37048067, 2023).
atrophic gastritis (3 papers, 2014 to 2025). "Among studies that included pediatric patients, the expression of MUC5AC, MUC6 and MUC2 were all increased in patients with intestinal metaplasia, but no data was available for gastric atrophy." (PMID 33322136, 2020).
chronic sinusitis (3 papers, 2014 to 2024). "In human sinusitis mucosa, which is supposed to be hypoxic, expression of MUC5AC and HIF-1α is higher than in control mucosa." (PMID 24840724, 2014). "We also confirmed MUC5AC expression in human tissue with immunohistochemical staining, and it was strongly expressed in epithelium from sinusitis compared to control tissue." (PMID 24840724, 2014). "The results indicate that anoxia up-regulates MUC5AC by the HIF-1α signaling pathway in human nasal epithelia and suggest that hypoxia might be a pathogenic mechanism of mucus hypersecretion in sinusitis." (PMID 24840724, 2014). "In sinusitis, the expression of MUC5AC, a major respiratory mucin gene, increases." (PMID 24840724, 2014). "In the specimens from sinusitis patients, over-expression of HIF-1α and MUC5AC was observed by immunohistochemistry." (PMID 24840724, 2014). "Therefore, increasing the oxygen tension in the sinus may result in improvement in sinusitis by reducing MUC5AC production, and modulation of HIF-1α activity should be considered as a new target for the treatment of sinusitis." (PMID 24840724, 2014).
co-infection (3 papers, 2019 to 2025). "In vivo co-infection studies with M. gallisepticum and subsequent E.coli revealed an activation of the IL-17 pathway and increased levels of inflammatory mediators, such as mucin-5 subtype AC (MUC5AC)." (PMID 36056451, 2022). "QPCR analysis showed that the expression trend of 10 genes between the co-infection and control groups (IL-17C, NFκB, AP1, C/EBPβ, CXCL1, CXCL8, MMP1, MMP3, GM-CSF, and MUC5AC) was consistent with the RNA-seq results." (PMID 31803158, 2019).
Gastric Metaplasia (3 papers, 2009 to 2024). Intestinal metaplasia of the gastric mucosa is an intermediate precancerous gastric lesion in the gastric cancer cascade from chronic gastritis and atrophy to dysplasia and adenocarcinoma. "The prevalence of gastric metaplasia has been reported in intestinal inflammatory diseases including CD and non-specific chronic duodenitis, and the expression of MUC5AC was detected in UC." (PMID 37574502, 2023). "So, an area with gastric metaplasia within the specialized Barrett's epithelium could originate an expansion clone capable of initiate the carcinogenesis cascade, developping an undifferentiated adenocarcinoma, that express MUC5AC." (PMID 19272137, 2009).
gastrointestinal carcinomas (3 papers, 2016 to 2023). "MUC1, MUC2 and MUC5AC are more significant than any other mucins for the differential diagnosis of PMOC and MMOC, particularly in gastrointestinal carcinomas." (PMID 37664708, 2023). "MUC1, MUC2 and MUC5AC are dominant in MOC and can be used in the differential diagnosis of PMOC and MMOC, particularly in gastrointestinal carcinomas." (PMID 37664708, 2023).
hay fever (3 papers, 2013 to 2026). "The MUC5AC TR genotype variable showed marginally significant association with hay fever (P = 0.044) but was not significant with any other outcomes." (PMID 23551418, 2013).
helminth infections (3 papers, 2015 to 2025). "Previous studies in mice have also shown a protective role for MUC5AC (murine) in helminth infection, suggesting that MUC5AC expression in the gastrointestinal tract is a tissue-protective response." (PMID 40177488, 2025). "Muc5ac is also expressed in the intestine upon clearance of helminth infections." (PMID 26162072, 2015). "Interestingly, Muc5ac is also up-regulated in the intestine following helminth infection and required for expulsion, suggesting a key role for coordinated mucus responses in immunity to helminth infections at multiple barrier surfaces." (PMID 31582416, 2019).
invasive carcinoma (3 papers, 2020 to 2022). A carcinoma that is not confined to the epithelium, and has spread to the surrounding stroma. "This is particularly evident for GIO and DIO mT models that showed an increase of invasive carcinoma compared to the lean mice models as well as a regulation of two pancreatic carcinoigenesis MUC5AC and MUC6." (PMID 32411709, 2020). "The pathological findings revealed invasive carcinoma derived from IPNB, and immunohistochemistry revealed positive expression of MUC1, MUC5AC, and MUC6, but negative expression of CDX2 and MUC2." (PMID 33097064, 2020).
metastatic disease (3 papers, 2023 to 2024). "In particular, MUC16 levels have a strong association with metastatic disease, whereas MUC5AC has great efficacy in differentiating resectable early-stage PC from healthy controls, with significant sensitivity for disease detection when combined with CA 19-9 and almost 100% specificity." (PMID 39767746, 2024). "Nodal metastatic tumors showed extensive patchy for diastase-resistant PAS positivity and more focal Alcian blue staining, along with limited MUC5AC by immunohistochemistry." (PMID 38632190, 2024). "In a recent analysis, multiple mucins, including MUC1, MUC2, MUC5AC, and MUC6, were found to differentiate primary BC from metastatic BC, where MUC1 correlated with the low or early grade, MUC5AC with metastatic disease, and MUC6 emerged as an indicator of poor prognosis." (PMID 36980526, 2023).
Nematode Infection (3 papers, 2011 to 2015). "Proliferation of intestinal goblet cells is a prominent feature of the type 2 immune response to nematode infection and both Muc2 and Muc5ac are important for worm expulsion." (PMID 26377648, 2015). "The immunohistochemical experiments performed in this study demonstrated a significant increase in expression of not only Muc5AC but also Muc2 protein in goblet cells after nematode infection." (PMID 27335862, 2013). "On the other hand, MUC5AC was found to be strongly downregulated in the abomasum of sheep infected with Haemonchus contortus, as well as in experimentally infected sheep selected for resistance to nematode infections." (PMID 21569362, 2011). "Taken together, it was shown that nematode infection induces airway goblet cell hyperplasia, which is characterised by the overproduction of Muc2 and Muc5AC core peptides and of the nonmucin secretory peptide Retnlb." (PMID 27335862, 2013).
Obesity (3 papers, 2022 to 2025). Accumulation of substantial excess body fat. "Studies have found that HHIP (hedgehog interacting protein), MUC5AC, CYP2A6, and PCK1 can promote obesity." (PMID 38137330, 2023).
ovarian tumors (3 papers, 2009 to 2015). "In addition, the ovarian tumors that showed a high level of expression of blood group antigens also revealed a strong reactivity towards the MUC5AC antibody." (PMID 26075384, 2015). "Various studies have shown the overexpression of MUC1, MUC2, MUC3, MUC4, MUC5AC and MUC16 in a variety of ovarian tumors." (PMID 20034397, 2009). "Different studies on the expression of mucins in ovarian tumors have shown overexpression of MUC1, MUC2, MUC3, MUC4, MUC5AC and MUC16 or CA125." (PMID 20034397, 2009). "The much higher expression of mucins (MUC1, MUC4, MUC5AC, MUC13 and MUC16) in ovarian tumors compared to the surrounding normal tissues can be exploited for the purpose of radioimmunodiagnosis (RID) and radioimmunotherapy (RIT)." (PMID 20034397, 2009).
Pneumocystis infection (3 papers, 2019 to 2024). "Induction of the CLCA1 pathway with increased mucins has been shown to correlate with Pneumocystis infection in humans and in animal models and is strongly related to IL-13 driven mucus cell metaplasia, STAT6 activation and MUC5AC and MUC5B expression in the airways." (PMID 31333624, 2019).
pterygium (3 papers, 2009 to 2022). A wedge-shaped fibrovascular lesion arising from the bulbar conjunctiva and extending to the cornea. "Among those DE-mRNAs, matrix metallopeptidase 3(MMP-3), fibronectin 1 (FN1), tenascin C (TNC), LRRC15, KRT6A, COMP, AKR1B10, and MUC5AC were significantly upregulated, which was consistent with previous studies on pterygium." (PMID 36398070, 2022). "An early microarray study reported increased expression of MUC5AC and the related MUC5B in pterygium, while another study reported almost total loss of MUC5AC in pterygium, as assessed by immunostaining." (PMID 34769520, 2021). "In pterygium, there was elevation of transcript and protein expression of MUC5AC and MSMB." (PMID 19272163, 2009). "However, the intensity of MUC5AC staining in pterygium was stronger than that in conjunctiva." (PMID 19272163, 2009). "Our results show that protein expression levels for keratin 6, CEACAM5, CD24, MSMB and MUC5AC were increased, whereas NR4A2 and IGFBP3 were reduced in pterygium, consistent with the transcript changes detected by the microarray analysis." (PMID 19272163, 2009). "We observed increased MUC5AC expression in pinguecula, but not in pterygium." (PMID 34769520, 2021).
villous adenoma (3 papers, 2006 to 2021). An epithelial neoplasm morphologically characterized by the presence of a villous architectural pattern. "Colonic villous adenoma-like growth pattern and immunohistochemical profile of MUC2-, MUC5AC- and CDX2-positivities but MUC1- and MUC6-negativities in the present case indicated that the lesion was consistent with the intestinal type IPMN." (PMID 34674710, 2021).
adenocarcinoma of the cervix (2 papers, 2020 to 2021). "This study further analyzed the relationship between the expression of MUC5AC and clinicopathological features in cervical adenocarcinoma." (PMID 32843061, 2020). "Among 52 cases of usual type cervical adenocarcinoma, 41 cases were MUC5AC positive, and 45 cases were CK7 positive, and there was no statistical difference (P = 0.448)." (PMID 32843061, 2020). "Moreover, the expression of MUC5AC was correlated with the degree of tumor differentiation in adenocarcinomas (P = 0.036) and was not related to the prognosis of cervical adenocarcinoma and subtypes." (PMID 32843061, 2020).
adenosquamous carcinoma (2 papers, 2020 to 2025). A carcinoma composed of malignant glandular cells and malignant squamous cells. "Immunohistochemical positivity for CK7 and MUC5AC and negativity for TTF-1 and p63 aid in differentiating MEC from adenosquamous carcinoma and metastatic lesions." (PMID 41487813, 2025).
allergic conjunctivitis (2 papers, 2015 to 2021). "In the conjunctiva of an experimental allergic conjunctivitis mouse model, the number of filled goblet cells reduced, and MUC5AC and MUC4 mRNA levels decreased by the repeated instillation of allergens." (PMID 34194821, 2021). "In mouse model of allergic conjunctivitis, repetitive application of allergens (cat danger or peptide P3-1) reduces the number of secretary granule-filled goblet cells and a decrease in Muc5AC and Muc4 mRNA measured by real-time RT-PCR." (PMID 26818460, 2015).
ampullary carcinoma (2 papers, 2011 to 2024). "The expression of MUC5AC is associated with better prognosis for ampullary carcinoma, and with better survival of invasive ductal carcinoma of the pancreas." (PMID 22027009, 2011). "Another study on ampullary carcinoma, which set the cutoff for MUC5AC positivity at either >25% or 1%, reported significant survival differences between MUC5AC-positive and MUC5AC-negative patients, regardless of the histological subtype." (PMID 38893239, 2024). "Our findings provide limited evidence suggesting that MUC5AC may be a significant prognostic factor for ampullary carcinoma." (PMID 38893239, 2024). "However, the prognostic value of MUC5AC in ampullary carcinomas remains controversial." (PMID 38893239, 2024).
atopic dermatitis (2 papers, 2019 to 2025). "We have reported that the expression level of SPDEF mRNA, a differentiation marker of goblet cells, correlates with MUC5AC mRNA in ocular surface tests of patients with atopic dermatitis." (PMID 40861543, 2025). "For this reason, it is important to evaluate the presence or absence of corneal epithelial disorders before initiation of eyewash use, and we will investigate the mucins other than MUC5AC and MUC16 and the efficacy of eyewash use in patients with atopic dermatitis in the future." (PMID 31614909, 2019).
bacterial pneumonia (2 papers, 2012 to 2022). Acute infection of the lung parenchyma caused by bacteria (e.g., Streptococcus pneumoniae, Haemophilus influenzae, Chlamydia pneumoniae, Mycoplasma pneumoniae, and Legionella pneumophila). "Therefore, GOL can effectively reduce the expression of MUC5AC before bacterial pneumonia causes lung injury." (PMID 35518345, 2022). "BPIFB1 was localized in CF lung samples along with BPIFA1, MUC5AC, CD68 and NE and directly compared to histologically normal lung tissues and that of bacterial pneumonia." (PMID 22767025, 2012).